IL6 (interleukin 6)
Diseases named in the same sentence as IL6 in open-access papers (continued):
Sharing a sentence is not in itself a finding about the gene and the disease.
infection (continued). "Expectedly, infection of P.a (2.5×106 CFU/mice), resulted in a sharp increase in neutrophils associated with increased levels of KC, IL-6, TNFα, IL-1β and IL-12 in BAL fluids compared to non-infected mice." (PMID 25605549, 2015). "TRIM30α deficiency or knockdown enhanced the production of type I IFNs and the inflammatory cytokine IL-6 upon stimulation with intracellular DNA or infection with the DNA viruses HSV-1 or VACV in BMDCs and D2SC cells." (PMID 26114947, 2015). "IL-6 is an important cytokine involved in infection and in traumas, and is secreted primary by T cells and macrophages." (PMID 25816137, 2015). "Apart from the TH2 cytokines, IL-6 and IL-17 were detected in peripheral blood during the first three days of infection." (PMID 26135397, 2015). "HOIL-1 KO mice chronically infected with M. tuberculosis also exhibited increased expression of both IL-6 and TNFα in serum at 70 days post-infection." (PMID 25599590, 2015). "In particular, elevated IL-1β and IL-6 serum levels have been identified as markers of severity in acute lung injury during infection by the influenza A (H1N1) pdm09 virus, specifically among patients who do not respond to conventional antiviral treatments." (PMID 26657940, 2015). "MGAS315 infection sites had higher levels of IL-6 than MGAS6180 sites, suggesting that the hypervirulent phenotype of MGAS315 is not due to a suppressed IL-6 response." (PMID 26047469, 2015). "Expression of IL-6 is induced during inflammation, infection, trauma, and stress as a consequence of induction by stimuli including IL-1, Tumor Necrosis Factors (TNF), Lipopolysaccharide (LPS) and Toll-Like receptor ligands." (PMID 25961579, 2015). "To compare the impact of MyD88 on host and viral gene expression directly, we measured the expression kinetics of Tnf, Il6 and Ifnb1 with the viral Ie1 gene in the context of the infection of Myd88-/- and WT BMDMs." (PMID 25856589, 2015). "Inflammation and infection can also stimulate hepcidin synthesis by hepatocytes through interleukin-6 (IL-6) and activation of the STAT-3 signaling pathway." (PMID 26270641, 2015). "Interleukin‐6 (IL‐6) participates in the host response to injury and infection in the central nervous system (CNS)." (PMID 25903009, 2015). "The cytokines IFN-alpha, IFN-gamma, IL-1β and IL-6 became significantly induced following infection with NDV-CA02 in chicken splenocytes in vitro during early-phase post-infection." (PMID 26635752, 2015). "TP3 treatment caused a decrease in TNF-α, IL-6, and CXCL5 at the site of infection on days 1, 3, and 5; on the other hand, MRSA infection induced TNF-α and IL-6." (PMID 25992774, 2015). "IL-6 was detected in the HEK293 cells following infection with miRT-H1N1, scbl-H1N1, or wt H1N1 at 24 hpi." (PMID 25788763, 2015). "As gender and IL-6 levels had significant relationship with mortality, to determine possible interdependency of these variables with comorbids and site of infection, logistic regression analysis was performed." (PMID 26649014, 2015). "qPCR analysis showed that shSOCS3 expression by Lenti-shSOCS3 infection led to a significant reduction in IL-6-induced SOCS3 mRNA expression." (PMID 26384335, 2015). "The IL-6 is an important proinflammatory cytokine involved in the regulation of host response to tissue injury and infection." (PMID 26644840, 2015). "Surprisingly, in addition to significantly attenuated serum TNF-α and IL-6 levels, mMrp8-tolerised mice showed significantly reduced bacterial counts in the circulation and visceral organs in response to polymicrobial infection." (PMID 26329314, 2015). "As the infection developed, the ratio of Treg increased, the level of IL-6 decreased to a normal level, and IL-2 sharply increased." (PMID 26599407, 2015). "After infection, the kinetics of IL-8 and IL-6 production were comparable for CF and CTRL cells (respectively)." (PMID 26485688, 2015).
infection (continued). "Interleukin-6 is a cytokine involved not only in inflammation and infection responses but also in the regulation of metabolic, regenerative, and neural processes." (PMID 25629046, 2015). "Both subcutaneous MGAS315 and MGAS6180 infections induced very low levels of TNF-α but MGAS315 induced significant levels of IL-6 and low levels of IFN-γ in blood." (PMID 26047469, 2015). "IFNγ and IL-12 mRNA were upregulated at all time points, whereas TNFα and IL-4 upregulation started at day 14 and IL-6 mRNA only increased at day 19 post infection." (PMID 26481427, 2015). "Suppressive effects outweighed transcriptional activation that resulted in less IL-6 production in cells undergoing productive infection compared to controls." (PMID 25573478, 2015). "March5+/− mice produced higher levels of serum IFN-β and interleukin (IL)-6 than March5+/+ mice in response to infection with VSV-GFP (green fluorescent protein) virus or injection of poly(I:C)." (PMID 26246171, 2015). "During TB disease, several cytokines are released as an immune response against M. tb and IL-6 plays a critical role in limiting the infection." (PMID 26241963, 2015). "Cytokine mRNA quantification showed increased levels of IFNγ, TNFα, IL-4, IL-6, and IL-12 during infection." (PMID 26481427, 2015). "Analysis of the cytokine and chemokine responses in the lung showed that D39, but not D39Δcps pneumococci despite higher bacterial numbers, triggered the production of TNF-α, IL-6 and KC in the lung 6 hours after infection." (PMID 25700108, 2015). "The control group of patients with infections other than IE showed an elevated proportion of high producers of IL-6 and IL-8 and a moderate prevalence of high producers of IL-10." (PMID 26225421, 2015). "IL-6 is released by T cells and macrophages as an immediate immune response during infection and tissue damages which leads to inflammation, as such they play an important role in acute inflammation and immune regulation." (PMID 26694339, 2015). "In summary, the expression of Il-6 was most significantly increased during the early period of DTMUV infection and the type I Ifns played a key role in the duck’s response to DTMUV in the same period." (PMID 26005441, 2015). "The presence of both IL-4 and IL-6 during the clearance phase of infection, when TNFα and IFNγ levels are exceedingly high, protects the colonic epithelial surface against more detrimental damage." (PMID 26481427, 2015). "Despite low levels of TNF-α, IL-6 and KC in the lung early after infection, D39Δcps induced profound lung inflammation like D39, as determined by semi-quantitative pathology scores of lung tissue slides and by measuring neutrophil influx." (PMID 25700108, 2015). "Interleukin 6 (IL-6), a cytokine secreted by T cells and macrophages, is produced at the inflammation sites during infection and tissue damage." (PMID 25785232, 2015). "IL-6 is secreted by T lymphocytes and macrophages during infection, stimulating immune response and serving as a pro-inflammatory mediator." (PMID 26126965, 2015). "In HBE cells infected with scbl-H1N1 or wt H1N1, IL-6 was upregulated to over 600- and 700-fold, respectively, while, in infection with miRT-H1N1, IL-6 induction was significantly lower." (PMID 25788763, 2015). "The amount of IL-6 in the culture media of DV2-infected PBMC increased significantly from day 2 to day 5 post-infection as compared to that of the mock-infected PBMC." (PMID 26226614, 2015). "The percentage of Th17 steadily increased as the infection developed, suggesting that an alternative pathway polarizes Th17 cells in addition to the IL-6 and TGF-β1 signaling pathways." (PMID 26599407, 2015). "Glial secretion of interleukin-6 (IL-6), along with other pro- and anti-inflammatory cytokines and chemokines, is drastically increased in response to infection or harmful changes in the brain." (PMID 26434635, 2015).
infection (continued). "The fact that piglets suckling the basal fed sows displayed increased expression of IL-1 and IL-6 in response to LPS suggests that these animals retained a capacity to respond more adequately to infection relative to the piglets suckling SDP-supplemented sows." (PMID 26495119, 2015). "Infection with Mex4487 influenza virus induced a strong increase in IL-6 and MCP-1 in the blood in cynomolgus macaques at day 1 after influenza virus infection and a gradual increase in IL-8." (PMID 25946071, 2015). "In general, there was an increasing trend observed in the IL-6 expression of those responsive DV2-infected wild-type mice from day 1 to day 5 post-infection." (PMID 26226614, 2015). "Similar decreases in Tnf and Il6 mRNA were observed in mice on the Rag1−/− background at 3 hr post-infection, confirming that these differences are due to a defect in innate immunity in the absence of HOIL-1." (PMID 25599590, 2015). "Palmitate-induced increases of IL1β and IL6 mRNA levels were still detected after the infection of Ad-SIRT3LF or Ad-SIRT3SF." (PMID 25915406, 2015). "In this study, we documented significantly increased pro-inflammatory cytokines including TNF-α, IL-17, IL-6 and IL-1β in serum at 6 wks post-infection, at which time mating occurred." (PMID 26322971, 2015). "Most of the ISGs and cytokines, including IFNβ, IFIT2, TNFα, and IL6 were detected two hours post-infection." (PMID 25728279, 2015). "It is of interest, therefore that expression of IL-1α is relatively low at early times, increasing more than 6 fold in EP infected chambers at later times of infection, at the same time as IL-6 expression is being reduced." (PMID 26171605, 2015). "Infection with L. monocytogenes led to significantly higher IL-8 and IL-6 than L. innocua expressing InlB, which correlates with increased ISG15 expression." (PMID 26259872, 2015). "As IFNγ and TNFα levels increase during clearance of infection, the concomitant increase in IL-4 and IL-6 protects mitochondrial function." (PMID 26481427, 2015). "Significantly lower IL-6 was detected in infection with miRT-H1N1 compared with scbl-H1N1 or wt H1N1." (PMID 25788763, 2015). "Initially, at 48 h post-infection, as expected, IL-6 (14.21-fold change) mRNA expression in the ceca from S. Enteritidis-infected chickens was up-regulated when compared to the expression in the cecum from the non-infected birds." (PMID 26664962, 2015). "In WT mice, when the concentrations of IFNγ and TNFα increase during clearance of infection, the concurrent induction of IL-4 and IL-6 thus appears to protect the mitochondrial function of the colonic epithelium from further damage." (PMID 26481427, 2015). "In fact, we confirmed that ablation of Sirt2 in BMDM led to increased levels of IL-6 upon infection with M. tuberculosis." (PMID 26135889, 2015). "The cytokine environment during the course of infection was different in IFNγ−/− compared to WT mice, mainly with regards to that IL-4 and IL-6 were upregulated already by day 10 post infection (3-fold vs 20-fold)." (PMID 26481427, 2015). "Duck myotubes infected with the same high-pathogenicity virus displayed a weak proinflammatory response, with downregulation of TNF-α and IL-6 at 24 h of infection." (PMID 25540384, 2015). "It is reported that interleukin-6 can stimulate hepatic production and secretion of secretory nonpancreatic phospholipase A2 (sPLA2), an acute-phase protein that is increased during infection and inflammation." (PMID 26503474, 2015). "The release of IL-6 and IL-10 in the spleens of animals dying during the acute phase of infection was similar in all three groups (P > 0.05)." (PMID 25563481, 2015). "We also detected significant differences in IL-8 and IL-6 production after infection in CF and CTRL cells." (PMID 26485688, 2015).
infection (continued). "Cytokine and chemokine levels in whole lung homogenates were not different between Nod2-/- and Wt mice with the exception of IL-6 concentrations, which were higher in lungs of Nod2-/- mice 24 hours after infection (P<0.05)." (PMID 26673231, 2015). "We found elevated IL-6 levels in lung homogenates taken from Nod2-/- mice at 24 and 48 hours post-infection (P<0.05 and P<0.01)." (PMID 26673231, 2015). "IL-6 is secreted by macrophages and T cells to stimulate immune response during infection or trauma." (PMID 25762865, 2015). "The amounts of cytokines, Tnfα Interleukin 6 (Il6) and Ifnγ in the sera increased significantly by day 4 post infection in both C57BL/6 and Nos2-/- mice." (PMID 26029930, 2015). "In a murine model, the production of hepcidin during a blood-stage infection can prevent a subsequent liver-stage infection; this inhibition was preserved in mice treated with anti-IL-6 antibodies." (PMID 26466783, 2015). "The expressions of IL-1β and IL-6 mRNA were down-regulated at 5 days after infection when comparing with A. fumigatus infection at 3 days in the 1-MT treatment group as well as in the PBS treatment group." (PMID 26361229, 2015). "The release of IL-6 during cold or flu is also critical in coordinating the innate and adaptive immune responses for efficient clearance of infection." (PMID 25788896, 2015). "Bacterial-induced host proteins such as procalcitonin, C-reactive protein (CRP), and Interleukin-6, are routinely used to support diagnosis of infection." (PMID 25785720, 2015). "As high serum levels of pro-inflammatory cytokine IL-6 have been shown to contribute to severity of S. aureus infection, we determined the levels of serum IL-6 in wild type, C5aR1−/−, and C5aR2−/− mice at 24 h after intravenous infection with S. aureus." (PMID 26512700, 2015). "SBCMV infection of this IBRB Tricell mixture for 96 hours resulted in increased levels of IL-6, MMP9, and stem cell factor with a concomitant decrease in granulocyte-macrophage colony-stimulating factor and TNF-alpha." (PMID 25573478, 2015). "It is noted that Tnf and Il1b mRNA expression were sustained at D5 post RSV-LD infection, while Il6 mRNA was only induced acutely at early times of infection, corresponding with the peak of weight loss." (PMID 26336095, 2015). "Quantitative RT-PCR analysis revealed a 3 fold increase in IL-6 mRNA levels in tongues harvested from mice following repeated infection with P. gingivalis/F." (PMID 26158901, 2015). "Levels of cytokines that showed large differences between EP and S. mitis (IL-1α, IL-6, KC, M-CSF and TNFα) were assayed in chamber fluid collected at 24 and 168 h after infection with the individual species." (PMID 26171605, 2015). "The protective immunity against the pathogen is mediated by cytokines such as IFN-γ, TNF-α, IL-12, IL-6 and IL-18 during the early stage of infection." (PMID 26359865, 2015). "Increased mortality due to ΔbgsA infection was associated with elevated plasma levels of the inflammatory cytokines TNF-α, IL-6 and MIP-2." (PMID 26172831, 2015). "The production of TNF-α, IL-6 and IL-8 by cervical lymph node MC was significantly higher for the control animals than for the infection or the re-infection group." (PMID 25252649, 2014). "The cells with depletion of EOLA1 were treated with LPS (100 ng/ml) at the point of 48 h post-infection and IL6 was detected by ELISA assay 6 h after LPS induced." (PMID 24916366, 2014). "In our study, after infection with S. japonicum for three weeks, cytokines (such as IL-4, IL-5, IL-6, IL-13, TNF-α and GM-CSF) in the sera of M. fortis were significantly increased, whereas cytokine levels of the BALB/c mice were much lower (data not shown)." (PMID 24886088, 2014). "IL-6 secretion significantly increased early at day 2 post-infection and quickly decreased to the level of the control, suggesting a correlation with the accumulation of macrophage." (PMID 24666970, 2014).
infection (continued). "When 100 cysts were used to infect mice, IL-6 production was significantly higher in TS mice only at 7 and 21 days of infection." (PMID 25437299, 2014). "Suzuki also reported that IL-6 mRNA was quickly induced at 24 h post-infection, but 8 h later, mRNA levels became dramatically lower." (PMID 24666970, 2014). "A similar IL-6-independent expansion of MLNC Th17 cells occurred following infection with another gastrointestinal nematode parasite, Nippostrongylus brasiliensis." (PMID 24185641, 2014). "In mouse models of infection, IL-1β, IL-6, and TNF-α are important protective cytokines during S. pneumoniae infection, and we have now demonstrated that expression of these cytokines by healthy controls was largely dependent on lipoproteins." (PMID 25172490, 2014). "Noteworthy, we observed induction of the Zc3H12a gene, whose product acts as an RNAse and can degrade mRNA encoding for IL6, in HIBCPP cells after infection with the MC58 strain." (PMID 25347003, 2014). "CCR5-/- mice were extremely susceptible to infection, presenting higher parasite load and lower tissue expression of IL-12p40, IFN-γ, TNF, IL-6, iNOS, Foxp3, T-bet, GATA-3 and PPARα." (PMID 25119429, 2014). "Ccl3, Ccl5, Tnfa, and Il6 were expressed at modest levels in unprimed RAW 264.7 cells upon infection, whereas pre-treatment of cells with IFN-γ strongly enhanced HSV1-induced gene expression." (PMID 25268627, 2014). "For the regulatory cytokine IL-10, and for the TH2 and TH17 cytokines such as IL-4, IL-6, and IL-17, our results indicate significant differences when comparing all primary infections with Leishmania spp." (PMID 25295285, 2014). "Yet, absence of MIF slightly increased survival time and reduced serum IFN-γ, TNF, and IL-6 concentrations while inducing IL-10 production in the chronic stage of infection." (PMID 25255103, 2014). "The first peak occurred early during infection, over days 3–7 post-challenge (CSG IL1 and IL6), while the second wave occurred during acute symptomatic infection over days 10–14 post-challenge (CSGs IL2, IL3, IL7–IL10)." (PMID 25014551, 2014). "Infection induces the release of cytokines and chemokines including tumor necrosis factor-alpha, interleukin 6, and interleukin 8, which have been proposed as mediators of cancer development." (PMID 24884867, 2014). "We have shown that HHV-8 infected MDDC in vitro display a Th2-skewed cytokine response characterized by a significant increase in IL-6, MIP1α, and MIP1β expression within 72 h post-infection." (PMID 25221546, 2014). "Antibody blocking of TLR2 or TLR4 before infection decreased epithelial IL-6 secretion (p = 0.0011 and p = 0.0047 respectively)." (PMID 24489729, 2014). "During the infection, high levels of IL-6 were detected in the serum of TS mice and TR mice presented high amounts of IFN-γ and TNF-α." (PMID 25437299, 2014). "The level of IL-6 and IL-8 dropped at 14 h post infection, when the parasite burden was also significantly lower compared to the parasite burden at 8 h post infection." (PMID 24886982, 2014). "EV-A71-infected cells treated with LiCl at various concentrations were examined for IL-6 and IL-1β production at 48 h post-infection." (PMID 25412347, 2014). "Proinflammatory cytokines, including TNF-α, IFN-γ and IL-6, have an important role not only in immune responses against infection but also in pathological inflammation." (PMID 24587010, 2014). "After infection by both T. gondii strains, all cells (microglial cells, endothelial cells, and neurons) synthesized mainly IL-6, IL-8, MCP-1 and GROα." (PMID 24886982, 2014). "The cytokine response in SABSI also appears to involve IL-6 elevation early in the course of infection although the levels were lower than those reported in Gram-positive sepsis." (PMID 25398383, 2014).